CCL18 (C-C motif chemokine ligand 18)
Diseases named in the same sentence as CCL18 in open-access papers (continued):
Sharing a sentence is not in itself a finding about the gene and the disease.
sarcoidosis (13 papers, 2010 to 2025). Sarcoidosis is a multisystemic disorder of unknown cause characterized by the formation of immune granulomas in involved organs. "The relative gene expression of CCL18 (an M2 associated marker) was significantly higher in sarcoidosis patients compared to healthy subjects (p = 0.034)." (PMID 20813038, 2010). "The identified EV biomarkers CCL18 could be implicated in the prediction of sarcoidosis-associated fibrosis." (PMID 41279897, 2025). "The serum concentration of C-C motif chemokine ligand 18 (CCL18) was observed to be markedly increased in individuals diagnosed with intrathoracic sarcoidosis." (PMID 41279897, 2025). "In our sarcoidosis cohort, CCL18 levels are increased in all patient groups, with a peak in fibrotic disease (with a median of 66,812 pg/mL vs. 59,317 pg/mL in the entire sarcoidosis cohort)." (PMID 37445972, 2023). "Accordingly, while studies have shown that CCL18 plays a role in fibrotic interstitial lung disease, higher CCL18 levels have been observed in lung diseases with a prominent lymphocytic inflammatory component, such as sarcoidosis." (PMID 37445972, 2023). "This concept becomes even more appealing thinking that some common cellular players such as M2 polarized macrophages, fibroblasts and molecular mediators (CCL18, TGFβ) are shared between fibrotic sarcoidosis and SSc." (PMID 36040491, 2022). "Diving deeper into the specific immune drivers of fibrotic sarcoidosis, in our view, the strongest data point to two broad groups of cells, Th17 cells in the adaptive immune system and CCL-18-expressing innate immune cells, and possibly macrophages via the recognition of PAMPS with TLR2." (PMID 36543347, 2022). "In sarcoidosis patients, elevated levels of CCL18 have been found in patients with active disease." (PMID 32760396, 2020). "Unfortunately, CCL18 is elevated in most interstitial lung diseases, and also in Gaucher's disease, so it is not suitable as a diagnostic biomarker for sarcoidosis." (PMID 32760396, 2020). "However, previous studies have reported that AM from sarcoidosis patients produce higher amount of the profibrotic cytokine CCL18, a mediator also overexpressed in IPF and SSc." (PMID 29562615, 2018). "Similarly to a previous study, we here demonstrate an increased gene expression of CCL18 in AMs of sarcoidosis patients as compared to healthy subjects." (PMID 20813038, 2010). "Currently, blood biomarkers such as ACE, sIL-2R, CD163, CCL18, serum amyloid A, and CRP are employed to aid in the diagnosis and monitoring of sarcoidosis." (PMID 39852350, 2024). "Additional serum biomarkers for sarcoidosis include neopterin, lysozyme, human cartilage glycoprotein-39 (YKL40), CD163, CCL18, serum amyloid A, and C-reactive protein (CRP)." (PMID 39852350, 2024). "When comparing the entire sarcoidosis cohort with the healthy cohort, the values for all markers (SAA, CCL18, CA15.3, CXCL9, CXCL10, and CTO) statistically significantly differ (p-values ≤ 0.001), except for SP-D (p-value = 0.23)." (PMID 37445972, 2023). "Patients with ground-glass lesions are a seemingly biochemically specific subgroup of intrathoracic sarcoidosis, with increased levels of SAA, CXCL9, CXCL10, CCL18, CTO, and CA15.3." (PMID 37445972, 2023). "All our sarcoidosis patients had increased serum concentrations of CXCL9, CXCL10, CTO, and CCL18." (PMID 37445972, 2023). "A much larger study of 102 sarcoidosis patients showed progressively increased levels of CCL-18 and CCL-17 (a CD4 T-cell chemoattractant), but not TNF-α, in BAL of Scadding stage 1–4 patients (n=32/35/23/12, respectively)." (PMID 36543347, 2022). "Non-lysosomal storage diseases with increased PARC/CCL18 levels include atherosclerosis, rheumatoid arthritis, beta-thalassemia, sarcoidosis." (PMID 36544230, 2022). "Thus, we speculate that the interaction of CCR6 and CCL18 might be pivotal for the progress of IPF, whereas in fibrosis, due to sarcoidosis or HP, these processes are obviously driven by other factors." (PMID 38334630, 2024).
sarcoidosis (continued). "For example, a simultaneously increased BAL fluid level of CCL18 and TGF-β1 secreting CCR6+ CD4+ T-cells would raise clinical suspicion of fibrosing sarcoidosis, and the clinician could consider prescribing anti-fibrotic agents to minimize the damage of future fibrotic scarring." (PMID 33036432, 2020).
hepatocellular carcinoma (12 papers, 2018 to 2025). A malignant tumor that arises from hepatocytes. "Hepatocellular carcinoma (HCC) is an aggressive malignancy, and CCL18, a marker of M2 macrophage activation, is often associated with tumor immune suppression." (PMID 38511143, 2024). "Metastasis was also supported by CCL18 secreting TAMs in pancreatic ductal adenocarcinoma (PDAC), head and neck squamous cell carcinoma (HNSCC), osteosarcoma, gallbladder cancer, hepatocellular carcinoma (HCC), NSCLC, gastric cancer." (PMID 34988021, 2021). "On the other hand, in lung adenocarcinoma cells and hepatocellular carcinoma cells, hypoxia does not change the expression of CCL18/MIP-4, probably because of the low expression of this chemokine in cancer cells compared to TAM which have the highest synthesis of CCL18/MIP-4 in a tumor." (PMID 32781743, 2020).
interstitial lung disease (12 papers, 2015 to 2026). A diverse group of lung diseases that affect the lung parenchyma. "CCL18 clearly functions in multiple different pathological conditions, such as tumor associated macrophages and interstitial lung disease, in addition to lysosomal diseases." (PMID 36721240, 2023). "CC-chemokine ligand 18 (CCL18) is the biomarker most consistently associated with outcomes in IPF and has been studied among several interstitial lung diseases." (PMID 32575869, 2020). "Krebs von den Lungen-6 (KL-6), surfactant protein-D (SP-D), and CCL18 have been considered as serum biomarkers of SSc-related interstitial lung disease." (PMID 33105647, 2020). "More recently, CCL18 was identified as a marker for early identification of progressive interstitial lung disease in systemic sclerosis (SS)." (PMID 30245686, 2018). "Increased CCL18 protein and higher CD163 mRNA were observed in lungs of patients with SSc-associated interstitial lung disease, suggestive of the presence of alternatively activated MØs." (PMID 28330499, 2017). "CCL18 is a chemokine produced by antigen presenting cells, particularly by alveolar macrophages in different interstitial lung diseases." (PMID 26168983, 2015). "In recent years, successful new candidate serum biomarkers have been identified for SSc-associated interstitial lung disease (ILD), including surfactant protein D (SP-D), Krebs von den Lungen 6 glycoprotein (KL-6), CCL18 and intercellular adhesion molecule 1 (ICAM-1)." (PMID 39156689, 2024).
bladder cancer (11 papers, 2012 to 2025). "At the same time, in the bladder cancer model, CCL18 causes an increase in the production of VEGF-C and matrix metalloproteinase-2 (MMP-2), which are factors involved in lymphangiogenesis." (PMID 33114763, 2020). "Conversely, high levels of other chemokines like CCL5, CCL8, CCL13, and CCL18 have been correlated with improved outcomes in bladder cancer patients." (PMID 39964621, 2025). "In bladder cancer, activation of CCR8 by CCL18 causes the migration and invasion of tumor cells, as well as increased expression of vascular endothelial growth factor (VEGF)-C, which then causes lymphangiogenesis." (PMID 35955670, 2022). "Expression of the CXC subfamily chemokines (CXCL9, CXCL10, and CXCL13) and of the CC subfamily chemokine CCL18 was consistently found to be higher in bladder cancer patients in the CLR-high group than in the patients in CLR-low group." (PMID 36131933, 2022). "As with CCL18 in bladder cancer, the biological functions seemed to be different from those of CXCL chemokines." (PMID 36131933, 2022). "In this study, we further investigated the association of two biomarkers, CCL18 and A1AT, with bladder cancer (BCa) and evaluated the influence of potentially confounding factors in an experimental model." (PMID 24011266, 2013). "Furthermore, in line with our findings, another CC chemokine ligand (CCL18) has been shown to play a critical role in the progression of bladder cancer." (PMID 32429318, 2020). "Moreover, in bladder cancer patients, the urinary concentration of CCL18 is higher than in healthy individuals." (PMID 33114763, 2020). "There are studies showed CCL18 may enhance migration and invasion by binding CCR8 in bladder cancer cells." (PMID 34893045, 2021). "In addition to PITPNM3, other receptors are also responsible for the CCL18-dependent migration and EMT of tumor cells, for instance CCR8 in bladder cancer cells." (PMID 33114763, 2020).
colon cancer (11 papers, 2017 to 2025). "Elevated CCL18 expression in colon cancer patients was significantly associated with both poorer RFS (n = 1336; HR = 1.33 [1.07–1.65]; p = 0.0099) and reduced OS (n = 1061; HR = 1.34 [1.09–1.65]; p = 0.0048)." (PMID 40692603, 2025). "Surgical stress has been shown to contribute to colon cancer progression by increasing cytokine levels of the C-C Motif Chemokine ligand 18 (CCL18) and T regulatory cell recruitment." (PMID 33353113, 2020). "Taken together, these results demonstrated that surgical trauma contributes to progression of colon cancer by upregulating CCL18 expression and hence promoting Tregs recruitment, resulting in an immunosuppressive environment." (PMID 30216450, 2019). "In the current study, we investigated whether surgical trauma contributes to the progression of colon cancer by upregulating CCL18 and recruiting Tregs." (PMID 30216450, 2019). "The expression of CCL18 in neoplastic cells is increased by the WNT→β-catenin pathway, as shown by in vitro experiments in the colon cancer and renal cell carcinoma models." (PMID 33114763, 2020).
melanoma (11 papers, 2012 to 2023). A malignant, usually aggressive tumor composed of atypical, neoplastic melanocytes. "In oral cancer cells, miR-205-5p has been found to promote IL-24 expression, whereas in melanoma cells, miR-205-5p has been found to inhibit CCL18 release via targeting its 3’UTR." (PMID 36435866, 2022). "In melanoma cells, colorectal neoplasia differentially expressed (CRNDE) long non-coding RNA (lncRNA) regulates miR-205, which causes CCL18 expression to increase." (PMID 33114763, 2020). "Moreover, in stage IV melanoma patients with brain metastases, CCL18, CCR1, CCR4, CD274, CSF2, EGF, and PTGS2 genes were significantly over-expressed (p < 0.001, versus patients without melanoma brain metastasis)." (PMID 37091783, 2023). "In addition, the data indicated that miR-205-5p expression negatively correlated with THBS1 in 449 skin melanoma samples, and that miR-205 affects the proliferation and metastasis of melanoma cells by targeting CCL18." (PMID 33186919, 2020). "The chemokine CCL18 produced by melanocytes itself can be increased and released under the induction of long non-coding RNA (LncRNA) CRNDE, and promote the proliferation, invasion, and metastasis of melanoma." (PMID 36131942, 2022).
glioblastoma (10 papers, 2020 to 2025). The most malignant astrocytic tumor (WHO grade IV). "Moreover, CCL18 production in glioblastoma is primarily attributed to tumor-associated macrophages (TAMs) and cancer-associated fibroblasts (CAFs), with a remarkably elevated level observed in glioblastoma compared to healthy brain tissue, exceeding it by more than 100-fold." (PMID 38365809, 2024). "In tumor-transformed brain tissue, there were areas with many macrophages (red arrows) that were metabolically active to synthetize and liberate CCL18 into ECM of glioblastoma (green arrows) within the region where hypoxia and malnutrition occurred." (PMID 35955670, 2022). "For instance, in glioblastoma multiforme, the concentration of CCL18 is over 100 times higher than in healthy brain tissue." (PMID 33114763, 2020). "While most of the analyzed chemokines (listed in Section 2) were not released by ferroptotic glioblastoma cells, we detected variations for CXCL1, CCL18, CCL20, and CCL22; however, these were not significant when comparing RSL3 to RSL3/liproxstatin-1." (PMID 41300529, 2025).
lung diseases (10 papers, 2010 to 2024). "Fibroblasts are regarded as important drivers of fibrotic lung diseases, and CCL18 has been reported to foster collagen and αSMA expression in fibroblasts." (PMID 38334630, 2024). "As the study was an expansion of a prior study designed to evaluate the role of CCL18 in predicting radiation-induced lung disease after radiotherapy, which included a heterogeneous group of thoracic malignancies." (PMID 34830880, 2021). "In fact, previous findings in arteriosclerosis and lung diseases support strong CCL18 expression by lesional macrophages and dendritic cells." (PMID 29338773, 2018). "The CC chemokine ligand 18 (CCL18) is produced by alveolar macrophages in patients with fibrosing lung disease and its concentration is increased in various fibrotic lung diseases." (PMID 28957436, 2017). "There have also been findings of high levels of CCL18 in patients with other fibrosing lung disorders." (PMID 20813038, 2010). "Enhanced CCL18 production has been verified in several inflammatory skin and lung diseases." (PMID 24612997, 2014).
osteosarcoma (10 papers, 2017 to 2025). A usually aggressive malignant bone-forming mesenchymal neoplasm, predominantly affecting adolescents and young adults. "High CCL18 levels in serum and osteosarcoma tissues derived from CD68 + M2 TAMs are associated with lung metastases development." (PMID 40442778, 2025). "CCL18 levels increased in the osteosarcoma tissues and serum of patients associated with lung metastasis." (PMID 39359731, 2024). "At least in osteosarcoma cells, CCL18 causes an increase in the expression of the urothelial carcinoma associated 1 (UCA1), which results in the activation of the WNT→β-catenin pathway." (PMID 33114763, 2020). "UCA1 overexpression, induced by TAM-derived CCL18 (C-C motif chemokine ligand 18), was closely associated with pulmonary metastasis and unfavorable clinical outcomes in osteosarcomas." (PMID 33050642, 2020). "The tumor-associated macrophage cytokine CCL18 (C-C Motif Chemokine Ligand 18) was significantly over-expressed in aggressive human osteosarcomas, and a clustering of mutations in the BAGE (B Melanoma Antigen) tumor antigen gene family was found." (PMID 29100308, 2017). "CCL18 also causes the migration of the osteosarcoma cell lines MG63 and 143B." (PMID 33114763, 2020). "Several TAM derived chemokines and interleukins including TGFβ, IL6, IL10, CCL2 and CCL18 are essential for metastatic bone sarcoma with most studies performed in osteosarcoma." (PMID 40442778, 2025). "CCL18 secreted from TAMs promotes osteosarcoma cell proliferation and migration via the EP300-UCA1-Wnt-β-catenin pathway." (PMID 39359731, 2024). "TAM-derived molecules, such as IL-1β and C-C motif chemokine ligand 18 (CCL18), significantly promote osteosarcoma metastasis." (PMID 39359731, 2024). "We also uncovered a significant over-expression of CCL18 in both aggressive human osteosarcomas that was not present in the curable human tumor." (PMID 29100308, 2017).
pancreatic ductal adenocarcinoma (10 papers, 2016 to 2023). An infiltrating adenocarcinoma that arises from the epithelial cells of the pancreas. "NF-κB activated by CCL18 is equally responsible for the increase in the expression of the vascular cell adhesion molecule-1 (VCAM-1) on pancreatic ductal adenocarcinoma cells." (PMID 33114763, 2020). "Notably, IHC of human pancreatic ductal adenocarcinoma and prostate cancer revealed that both cancer epithelial cells and mesenchymal macrophages express CCL18." (PMID 26919103, 2016). "It was reported that CCL18/PITPNM3 interaction could also promote liver cancer migration, invasion, EMT, and the progression of pancreatic ductal carcinoma." (PMID 36850011, 2023).
prostate carcinoma (10 papers, 2014 to 2025). A carcinoma that arises from epithelial cells of the prostate gland. "In addition, CCL18 had been reported as a cancer risk factor in both breast and prostate cancer." (PMID 38075694, 2023). "In contrast, the survival ability of prostate cancer patients indicated that CCL18 is more potential than the EGF." (PMID 40692603, 2025). "In conclusion, our data offer the convincing evidence that the upregulation of CCL18 may be involved in the tumor aggressive progression of prostate cancer." (PMID 25197632, 2014). "However, the origin of CCL18 may be cancer-type specific, because prostate cancer epithelial cells also secrete CCL18." (PMID 26919103, 2016). "Cochrane’s Q test did not provide evidence of heterogeneity between CCL18 (p = 0.767), CCL19 (p = 0.093), CCL24 (p = 0.935), CXCL17 (p = 0.210) and prostate cancer." (PMID 38075694, 2023).
systemic sclerosis (9 papers, 2017 to 2026). A chronic disorder, possibly autoimmune, marked by excessive production of collagen which results in hardening and thickening of body tissues. "Serum CCL18 concentrations reflect pulmonary fibrotic activity in patients with idiopathic interstitial pneumonias (IIPs) and systemic sclerosis with pulmonary involvement." (PMID 32575869, 2020). "CCL18 expression is increased in patients with systemic sclerosis and in hypersensitivity pneumonitis." (PMID 32575869, 2020). "Further research is needed to investigate whether genetic variation in the CCL18 gene influences serum levels and disease course in systemic sclerosis and hypersensitivity pneumonitis." (PMID 32575869, 2020). "CCL18, derived from alveolar macrophages (a cell type exposed directly to smoke) is a known mediator of fibrogenesis implicated in the smoking-related lung disease IPF, and in the ILD associated with systemic sclerosis, another disease where fibrocytes play a role." (PMID 38935158, 2024). "The serum level of CCL18 has been shown to predict survival in IPF and systemic sclerosis, including in depth analyses from data of two randomized controlled trials." (PMID 32630441, 2020). "Indeed, CCL18 is predictive for the outcomes of ILDs, with higher predictive values for CCL18 in both IPF and systemic sclerosis." (PMID 39768150, 2024).